SUZ12 (SUZ12 polycomb repressive complex 2 subunit)
Diseases named in the same sentence as SUZ12 in open-access papers (continued):
Sharing a sentence is not in itself a finding about the gene and the disease.
Intellectual Disability syndromes (3 papers, 2019 to 2025). "Furthermore, this approach can accurately classify variants of uncertain significance in EED and SUZ12, thereby identifying pathogenic variants in individuals with undiagnosed overgrowth/intellectual disability syndromes." (PMID 40922349, 2025). "In line with this, a group of related human developmental overgrowth syndromes, including the Weaver, Weaver-like, Cohen-Gibson, and Overgrowth and Intellectual Disability syndromes, appear to be caused by heterozygous mutations in EED, EZH2 or SUZ12." (PMID 35245348, 2022). "In line with this notion, several related human developmental syndromes, including the Weaver, Weaver-like, Cohen-Gibson, and Overgrowth and Intellectual Disability syndromes, have been linked to heterozygous, usually de novo, mutations in EED, EZH2, or SUZ12." (PMID 30807568, 2019).
liver cancer (3 papers, 2016 to 2024). An epithelial or non-epithelial malignant neoplasm that arises from the liver. "However, the SUZ12 protein is expressed at low levels in HBV‐associated liver cancer tissues, and improved prognosis was observed in high expression group." (PMID 39400513, 2024). "Notably, our findings suggest that miR24‐2 alters several related genes (pHistone H3, SUZ12, SUV39H1, Nanog, MEKK4, pTyr) and accelerates progression of liver cancer cells through Pim1 activation." (PMID 32030886, 2020).
retinoblastoma (3 papers, 2014 to 2024). A malignant tumor that originates in the nuclear layer of the retina. "In retinoblastoma, knockdown of SUZ12 reduced MMP2/9 protein expression." (PMID 39400513, 2024). "In conclusion, SUZ12 siRNA inhibited cell invasion and the expression of VEGF, MMP-2 and MMP-9 in SO-RB50 retinoblastoma cells." (PMID 25295075, 2014). "SUZ12 has been widely investigated; however, no studies regarding the role of the SUZ12 gene in retinoblastoma (RB) have been conducted." (PMID 25295075, 2014).
asthma (2 papers, 2024 to 2025). "Interestingly, a few genes such as NRM, PTPRE and SUZ12 were observed to be associated with Rheumatoid Arthritis, Asthma and Endometrial Stromal Sarcoma diseases, respectively, in humans and genes like SCNN1B associated with renal disease in cattle." (PMID 38674383, 2024).
clear cell renal cell carcinoma (2 papers, 2019 to 2021). "In renal clear cell carcinoma, higher expression of EZH2 and EED was significantly correlated with poor prognosis, whereas high levels of SUZ12 were associated with longer survival." (PMID 34202528, 2021). "Binding targets of SUZ12 and EZH2 were consistently enriched across all five cancer types, while targets of REST and SMAD4 were enriched in all cancers except for clear cell renal cell carcinoma." (PMID 31523055, 2019).
diffuse large B-cell lymphoma (2 papers, 2020 to 2024). "It selectively degraded EED (Dmax = 95%), EZH2 (Dmax = 95%), and SUZ12 (Dmax = 80%), and it was observed that the proliferation of both the EZH2 mutant diffuse large B-cell lymphoma (DLBCL) cell line and the EZH2 wild-type (WT) rhabdoid cancer cell line was effectively suppressed." (PMID 38389844, 2024).
extranodal NK/T-cell lymphoma nasal type (2 papers, 2018). "Coactivation of PRC2 proteins (EZH2, SUZ12, and EED) were reported to be associated with inferior OS in NK T cell lymphoma." (PMID 29415665, 2018).
lymph node metastasis (2 papers, 2016 to 2017). "Univariate analysis demonstrated that invasive depth, tumor budding, expression of Suz12 at the TIF, T classification, lymph node metastasis and overall expression of miR-320a were statistically significant predictors of prognosis." (PMID 27582550, 2016).
meningioma (2 papers, 2020). A generally slow growing tumor attached to the dura mater. "An interesting finding was that the fastest growing cranial meningioma (P6_C1) carried one-copy loss of ARID1A and SMARCE1, the subunits of SWI/SNF, and one-copy gain of SUZ12 and EZH1, the components of PRC2." (PMID 32724039, 2020). "Gene ontology analysis revealed enrichment of SUZ12 and FOXM1 transcription factor networks and mitotic spindle function in the intracranial meningioma samples, consistent with the established roles of these pathways in regulating meningioma cell proliferation." (PMID 32517746, 2020). "In contrast, genes enriched in the liver metastasis showed overrepresentation of metabolic pathways, and SUZ12 and hepatocyte nuclear factor 4a (HNF4A) transcription factor networks, suggestive of liver-enriched gene expression programs, rather than metastatic meningioma." (PMID 32517746, 2020).
metastatic disease (2 papers, 2011 to 2013). "Additional changes we observed that we believe are important in the regulation of hMSC homing and invasion based on previous research by our lab and others include increases in gene members of the Glinsky Signature (SUZ12 and EZH2), which determine likelihood of death from metastatic disease." (PMID 24772452, 2013).
multiple myeloma (2 papers, 2018 to 2021). "Using Affymetrix microarrays, we analyzed the expression of PRC2 core genes EZH2, SUZ12, and EED in normal bone marrow plasma cells (BMPCs, n = 5), primary myeloma cells from patients (MMCs, n = 206), and human myeloma cell lines (HMCLs, n = 26)." (PMID 30285865, 2018). "Investigating the survival prognosis in multiple myeloma (MM) patients, we have shown that PRC2 core genes, EZH2, SUZ12 and EED, were significantly overexpressed in MM cells compared to normal plasma cells, making these cells sensitive to EPZ-6438, an inhibitor of EZH2." (PMID 34202528, 2021).
Pancreatic cancer (2 papers, 2019 to 2020). "Interestingly, the analysis identified enrichment of multiple TFs including TCF4, WT1, CEBPD, CEBPB, SUZ12, and ZFP281 across all stages of pancreatic cancer progression." (PMID 30644396, 2019).
soft tissue sarcoma (2 papers, 2020 to 2025). A malignant neoplasm arising from muscle tissue, adipose tissue, blood vessels, fibrous tissue, or other supportive tissues excluding the bones. "High SUZ12 and H3K27me3 expression correlates with poor survival in soft tissue sarcomas." (PMID 40949882, 2025).
spina bifida (2 papers, 2013 to 2015). A congenital neural tube defect in which vertebrae are not fully formed. "Interestingly, haploinsufficient SUZ12 mice exhibit cerebellar herniation, as well as spina bifida, an enlarged brainstem, and occipital cortical changes." (PMID 23620759, 2013).
T-cell leukemia (2 papers, 2021 to 2024). A malignant disease of the T-lymphocytes in the bone marrow, thymus, and/or blood. "STAT5B and SUZ12 at this level hold diagnostic value for T cell leukemias, while the remaining are relevant to other hematologic malignancies." (PMID 34299796, 2021).
thyroid cancer (2 papers, 2020 to 2023). "To determine whether EZH2/PRC2 components are deregulated in PTC and ATC, we first analyzed the expression of EZH2, EED and SUZ12 in BRAFV600E thyroid cancer cell lines." (PMID 37175580, 2023).
tongue squamous cell carcinoma (2 papers, 2017 to 2021). A squamous cell carcinoma that arises from the tongue. "In the present study, we sought to investigate the expression of SUZ12 and its clinicopathological significance in primary tongue squamous cell carcinoma (TSCC)." (PMID 28228691, 2017).
Uterine leiomyoma (2 papers, 2018 to 2020). The presence of a leiomyoma of the uterus. "SUZ12 and EED protein were detected in 18 of 32 (56.25%) and 14 of 32 (43.75%) LMS, respectively, and they were lower than that in uterine leiomyoma (16/16,100%) and normal myometrium (16/16,100%) (p < 0.05)." (PMID 30120321, 2018).
adenoma (1 paper, 2024). A neoplasm arising from the epithelium.
adenosarcoma (1 paper, 2020). A low grade malignant neoplasm characterized by the presence of a benign epithelial component (tubular and cleft-like glands) and a low grade sarcomatous component that contains varying amounts of fibrous and smooth muscle tissues. "Among the tumors in suz12 mutant fish, only an adenosarcoma with loss of two alleles had high levels of staining for H3K27me3." (PMID 32651197, 2020).
ameloblastoma (1 paper, 2021). The most common odontogenic tumor, arising from the epithelial component of the embryonic tooth and usually affecting the molar-ramus region of the mandible or maxilla. "The presence of patterns of five human PcG proteins (Bmi-1, Ring1b, Mel-18, Ezh2, and Suz12) in ameloblastomas and odontogenic keratocysts was previously analyzed." (PMID 33680332, 2021).
Anxiety (1 paper, 2020). Intense feelings of nervousness, tension, or panic often arise in response to interpersonal stresses. "SUZ12, TCF7L1, and BCL3 could bind to the CNR1 promoter region to regulate the expression of CNR1, which was associated with anxiety and chronic pain." (PMID 32434423, 2020).
autism spectrum disorder (1 paper, 2023). A spectrum of developmental disorders that includes autism, and Asperger syndrome. "The present results are aligned with reports that mutations in Suz12 have been associated with MIA-related autism spectrum disorder phenotypes." (PMID 37851674, 2023).
brain tumors (1 paper, 2010). "For this purpose, we queried the Oncomine database and found that 4 PcG genes (EZH2, RBBP7, SUZ12, YY1) are specifically expressed in brain tumors." (PMID 20920292, 2010).
carcinoma in situ (1 paper, 2018). "Data from immunohistochemical staining revealed that significant SUZ12 overexpression was observed in carcinoma (62.5%, 5/8), whereas much less were detected in healthy mucosa (16.7%, 1/6), samples with hyperplasia (16.7%, 1/6) or dysplasia/carcinoma in situ (50.0%, 3/6)." (PMID 29667751, 2018).
cardiomyopathy (1 paper, 2021). A disease of the heart muscle or myocardium proper. "The role of SUZ12 in cardiomyopathy is thus worthy of further investigation." (PMID 34692515, 2021).
craniosynostosis (1 paper, 2023). Craniosynostosis is defined as the premature fusion of one or more cranial sutures leading to secondary distortion of skull shape resulting in skull deformities with a variable presentation. "SUZ12 was significantly enriched for DEGs associated with lambdoid, sagittal, metopic, and coronal craniosynostosis from the primary model, and sagittal, metopic, and lambdoid craniosynostosis in the male sex-stratified model." (PMID 36982425, 2023). "Of this pair, SUZ12 has not previously been associated with craniosynostosis, but there are several studies reporting associations between EZH2 and craniosynostosis." (PMID 36982425, 2023). "All downstream DEGs of SUZ12 were directionally concordant across models and phenotypes, with 37 DEGs exhibiting increased expression and 37 DEGs exhibiting decreased expression, in craniosynostosis phenotypes compared to controls." (PMID 36982425, 2023).
embryonic carcinoma (1 paper, 2022). "To study CK2-mediated SUZ12 phosphorylation in vivo, we used shRNAs to knock down the CK2 subunit α, α′, or β in an embryonic carcinoma cell line NT2/D1." (PMID 36351927, 2022).
epilepsy (1 paper, 2013). A brain disorder characterized by episodes of abnormally increased neuronal discharge resulting in transient episodes of sensory or motor neurological dysfunction, or psychic dysfunction. "We found that genes downregulated in our epilepsy model (PILO and PILO + KD) shared binding motifs for neuron restrictive silencing factor (Nrsf) and suppressor of zeste 12 (Suz12)." (PMID 24005891, 2013).
Ewing tumors (1 paper, 2016). "Our results were in agree with Burdach and colleagues that demonstrated loss of regulation of both EED and SUZ12 expression in Ewing tumors." (PMID 27471434, 2016).
germinoma (1 paper, 2011). A malignant germ cell tumor arising in the central nervous system. "Although we had access to only a small number of RNA samples from the same tumours analysed for their methylation status, our data did reveal a significant difference between germinomas and YSTs in the level of expression of DNMT3B, but not EZH2 or SUZ12 (data not shown)." (PMID 21712824, 2011).
gliosarcoma (1 paper, 2021). A rare histological variant of glioblastoma (WHO grade IV) characterized by a biphasic tissue pattern with alternating areas displaying glial and mesenchymal differentiation (WHO).
Huntington disease (1 paper, 2022). Huntington disease (HD) is a rare neurodegenerative disorder of the central nervous system characterized by unwanted choreatic movements, behavioral and psychiatric disturbances and dementia. "Suz12 a component of the polycomb repressive complex 2 (PRC2), which has a well-established role in CNS development and neurodegenerative diseases, specifically in Huntington’s disease." (PMID 34650208, 2022).
infectious mononucleosis (1 paper, 2019). A condition characterized by an increase in mononuclear white blood cells and swollen lymph nodes, which is usually caused by infection with the Epstein-Barr virus. "ChIP-seq was performed to study the localization of BMI1 and SUZ12 across the host genome in an LCL produced by infection of 1o B cells with a recombinant EBV of B95.8 background (prototypical transforming EBV, originally derived from an infectious mononucleosis patient)." (PMID 30649516, 2019).
Insulin resistance (1 paper, 2025). Increased resistance towards insulin, that is, diminished effectiveness of insulin in reducing blood glucose levels. "TFs, such as Mef2d, which regulates mitochondrial biogenesis, and Suz12, which is involved in inflammatory gene regulation, provide molecular links to systemic glucose dysregulation and insulin resistance." (PMID 40076622, 2025).
leiomyoma (1 paper, 2018). A well-circumscribed benign smooth muscle neoplasm characterized by the presence of spindle cells with cigar-shaped nuclei, interlacing fascicles, and a whorled pattern. "SUZ12 and EED protein expression in LMS was deceased comparing with leiomyoma and myometrium." (PMID 30120321, 2018).
leiomyosarcoma (1 paper, 2019). An uncommon, aggressive malignant smooth muscle neoplasm, usually occurring in post-menopausal women. "These tumors lacked PRC2 (EED, SUZ12) mutations, and no mutations were present in RBL2 or SP100, two altered telomere maintenance genes found to be enriched in ALT-positive leiomyosarcomas." (PMID 31462295, 2019).
lentivirus infection (1 paper, 2018). Virus diseases caused by the Lentivirus genus. "SUZ12 protein was significantly reduced upon shSUZ12 lentivirus infection in both cells." (PMID 29667751, 2018).
malignant uterine tumors (1 paper, 2021). "The JAZF1/SUZ12 chimera was first demonstrated to inhibit apoptosis and induce proliferation rates above normal in both benign and malignant uterine tumors, although only in the malignant form was suppression of the wild type/unrearranged SUZ12 allele identified." (PMID 33099834, 2021).
medulloblastoma (1 paper, 2018). A malignant, invasive embryonal neoplasm arising from the cerebellum. "Multiple other genes belonging to PRC1 and PRC2 complexes, including BMI1, EED and SUZ12 have been found upregulated either in specific medulloblastoma subgroups or across medulloblastoma generally." (PMID 29759978, 2018).
nerve sheath tumor (1 paper, 2020). "The most frequently recorded SUZ12-mutated or SUZ12-deleted cancer type category is ‘nerve sheath tumor’, including MPNSTs (5.56% and 4.21%, respectively)." (PMID 32651197, 2020).
neuroendocrine carcinoma (1 paper, 2022). A malignant neuroendocrine neoplasm composed of cells containing secretory granules that stain positive for NSE and chromogranin. "CpGs of lower methylation in VP-MCC cell lines were associated with neuroendocrine marker genes such as SOX2 and INSM1, or linked to binding sites of EZH2 and SUZ12 of the polycomb repressive complex 2, i.e., genes with an impact on carcinogenesis and differentiation of neuroendocrine cancers." (PMID 34667274, 2022).
Obesity (1 paper, 2025). Accumulation of substantial excess body fat. "Additionally, it indicates that in children, both the "PAX3-FOXO1 target genes" and the "Suz12 target genes" are essential pathways that modulate both sleep and obesity." (PMID 40024983, 2025).
pancreatic adenocarcinoma (1 paper, 2020). "In the p53m/m, nf1b−/−, nf1a+/−, suz12-mutant cohort, all 28 tumor-bearing fish that were sectioned displayed MPNSTs, one of which also displayed the sole case of pancreatic adenocarcinoma (3.6%)." (PMID 32651197, 2020).
periodontitis (1 paper, 2025). An acute or chronic inflammatory process that affects the tissues that surround and support the teeth. "TFs, such as Ezh2 and Suz12, activated in periodontitis, provide additional mechanistic insights." (PMID 40076622, 2025). "Similarly, Suz12 may influence the balance between neuronal repair and inflammation, linking periodontitis with neurodegenerative diseases." (PMID 40076622, 2025). "Suz12, an epigenetic regulator, may favor reparative pathways by silencing inflammatory genes, reflecting a dynamic balance between inflammation and the resolution of periodontitis." (PMID 40076622, 2025).
prostate adenocarcinoma (1 paper, 2021). "Here we demonstrated that along with prostate adenocarcinoma, other tumor types show a correlation between high EZH2, SUZ12 and EED levels and a shorter survival, suggesting that these cancers could be potential targets for EZH2/SUZ12/EED inhibitor therapy." (PMID 34202528, 2021).
prostate neuroendocrine carcinoma (1 paper, 2021). "Detailed analysis of tumor subtypes identified CRPC and prostate neuroendocrine carcinoma as the tumors with the highest amplification rate (12–23%) of EZH2, SUZ12 and EED genes." (PMID 34202528, 2021).
pulmonary fibrosis (1 paper, 2023). Chronic progressive interstitial lung disorder characterized by the replacement of the lung tissue by connective tissue, leading to progressive dyspnea, respiratory failure, or right heart failure. "SUZ12 suppresses p27 and p27 promotes TGFB1 mediated pulmonary fibrosis." (PMID 37967122, 2023).
rhabdomyoma (1 paper, 2018). A benign mesenchymal tumor arising from skeletal or cardiac muscle. "The expressions of SUZ12 and RbAp46 protein were higher in RMS than in rhabdomyoma (p < 0.05)." (PMID 30120321, 2018). "SUZ12 and RbAp46 protein expression were observed in 37 of 51 (72.55%) and 35 of 51 (68.63%) RMS, respectively, and they were significantly higher than that in rhabdomyoma and TASM (p < 0.05)." (PMID 30120321, 2018). "SUZ12 and RbAp46 may be used as supplementary indicators together with EZH2 for differentiating RMS from rhabdomyoma." (PMID 30120321, 2018). "Moreover, the expression of SUZ12 and RbAp46 in RMS was higher than that in rhabdomyoma and TASM." (PMID 30120321, 2018).
squamous cell carcinoma (1 paper, 2018). A carcinoma arising from squamous epithelial cells. "In the 4‐nitroquinoline 1‐oxide (4NQO)‐induced HNSCC mouse model, increased SUZ12 immunostaining was observed along with disease progression from epithelial hyperplasia to squamous cell carcinoma in tongue." (PMID 29667751, 2018).
status epilepticus (1 paper, 2015). Status epilepticus is defined as a continuous seizure lasting more than 30 min, or two or more seizures without full recovery of consciousness between any of them. "Here, we explored the transcriptional response of genes associated with polycomb repressive complex (PRC) 1 (Ring1A, Ring1B, and Bmi1) and PRC2 (Ezh1, Ezh2, and Suz12), as well as additional transcriptional regulators Sirt1, Yy1, and Yy2, in a mouse model of status epilepticus (SE)." (PMID 25806020, 2015).